IL18 (interleukin 18)
Diseases named in the same sentence as IL18 in open-access papers (continued):
Sharing a sentence is not in itself a finding about the gene and the disease.
dermatitis (12 papers, 2016 to 2025). An inflammatory process affecting the skin. "IL-18, which independently causes AD-like skin inflammation and is associated with severity, and IL-33, an IL-1 cytokine family member that promotes Th2 inflammation and acts upstream in the cascade, were also elevated in the DNCB-induced Nc/Nga AD mouse model." (PMID 38139151, 2023). "The dermatitis was associated with a markedly increased concentration of serum IgE and IL18." (PMID 32687504, 2020). "However, the associations between soluble IL-6R variation and eczema/dermatitis or IL-18 and IBD within human populations are less well understood." (PMID 31276585, 2019). "The results showed that CBG improved dermatitis severity score, epidermal thickness, and mast cell count and reduced inflammatory cytokines (Tslp, Il1b, Il4, Il6, Il13, Il17, Il18, Il22, and Il33) by qRT-PCR (p < 0.001)." (PMID 39851511, 2025). "At a local level, studies that explored the expression of IL-18 at psoriatic skin lesions have reported significantly higher interleukin levels in cutaneous lesions compared to healthy skin samples from the same dermatosis patients." (PMID 34685372, 2021). "Using this framework, we found evidence to support causal relationships between levels of circulating IL-18 and IBD, as well as eczema/dermatitis, circulating soluble IL-6R and eczema/dermatitis and circulating IL-2Rα and MS, amongst others." (PMID 31276585, 2019). "There was strong evidence of association between circulating levels of IL-18 and IBD (P = 1.17 × 10−4) and eczema/dermatitis (P = 2.81 × 10−3)." (PMID 31276585, 2019). "Our results provide additional evidence to support these existing findings, as well as identifying monocytes and neutrophils as potential drivers of the relationship between IL-18 and eczema/dermatitis." (PMID 31276585, 2019). "IL18 is essential for the induction of dermatitis by the epidermis-restricted expression of caspase 1, the enzyme that generates active IL18 from its precursor." (PMID 27431613, 2016). "It has been presented that IL-18 is overexpressed in both AD patients and animal model, suggesting that IL-18 might play a certain role in the pathogenesis and development of dermatitis." (PMID 37325349, 2023). "In addition, expression of IL18 in keratinocytes induces a late-onset dermatitis associated with mastocytosis, but independent of IgE production." (PMID 27431613, 2016). "Both the analyses of IL-18 on IBD and on eczema/dermatitis survived leave-one-out analyses, as the removal of any individual SNP from the analysis had little effect on observed effect estimates." (PMID 31276585, 2019). "We addressed contribution of other IL‐1 cytokine family members to spontaneous skin inflammation in Flgft/ft mice but development of dermatitis in Flgft/ft mice was independent of IL‐33, IL‐18, and IL‐36." (PMID 30937919, 2019). "Severe dermatitis induced by repeated DNFB-application under SPF condition in NC/Nga was alleviated partially in NC.h2b/nc and significantly in NC.h2b/b as shown by decreased epidermal expression levels of TSLP and serum levels of total IgE, TSLP, IL-18 and IL-33." (PMID 29416104, 2018). "Thus, IL18 is not a determining factor in the context of the Δ/Δep2 dermatitis, which rather resembles a Th2/IgE-driven disease." (PMID 27431613, 2016).
eosinophilia (12 papers, 2009 to 2025). "IL-18-deficient mice develop enhanced allergen-induced eosinophilia, and IL-18-deficient mice are protected from helminth infections." (PMID 35281022, 2022). "IL-18 deficiency thus appears to promote allergic inflammation characterized by eosinophilia." (PMID 23283012, 2009). "Several studies have examined the role of IL-18 in the development of eosinophilia and have found that IL-18 plays a direct role in the maturation and induction of eosinophils." (PMID 40777291, 2025). "We showed that IL-18 is induced by Alternaria exposure and attenuates eosinophilia and production of IL-17A production in lung ILCs." (PMID 40777291, 2025). "Together, our findings suggest that IL-18 signaling prevents IL-17A production from ILC2s and subsequent eosinophilia in vivo." (PMID 40777291, 2025). "Taken together, we present the evidence on the role of IL-18–induced eosinophilia in the development of PC phenotype like ADM, PanINs, and ductal cell differentiation in inflammation-induced CP." (PMID 34183442, 2021). "In our study CCL-17, CCL-27 and IL-18 serum levels correlated positively with total IgE in Group 2, and eosinophilia correlated positively with CCL-27." (PMID 19639049, 2009). "ELISA analysis detected high levels of IL-18, which correlated with tissue eosinophilia." (PMID 37524769, 2023). "In AD patients below 10 years old (Group 1) a positive correlation between eosinophilia and CCL-20 (r = 0.53, P = .009) and IL-18 (r = 0.45, P = .03) was noted while in Group 2 eosinophilia correlated positively with CCL-27 (r = 0.52, P = .03)." (PMID 19639049, 2009). "Excess IL-18 protected against airway eosinophilia and Th2 differentiation in HDM in Il18tg but not Il18bp-/- mice, possibly due to minimal induction of IL-18 in the latter." (PMID 36096831, 2022). "IL-18, IL-12 and IFN-γ gene-expressing plasmids or transferred by an adenovirus vector can prevent and reverse established allergen-induced airway hyper-reactivity, airway eosinophilia and Th2 cytokine production." (PMID 19531238, 2009). "A relevant study reported that IL-18 and IL-12 inhibit antigen-induced airway hyper-responsiveness, lung eosinophilia, and serum IgE, but IL-18 or IL-12 alone failed to modulate any of these allergic responses." (PMID 23283012, 2009). "In our study, the cytokine profile of peptide 23-immunized mice depicting elevated CCL17, CCL22, and IL-18 might have contributed to the antiviral responses rather than the induction of lung inflammation, in which no significant eosinophilia was observed." (PMID 21980478, 2011).
gingivitis (12 papers, 2014 to 2025). A disorder involving inflammation of the gums; may affect surrounding and supporting structures of the teeth. "Higher concentrations of IL-18 have been detected in GCF of Pd patients compared to those with gingivitis, supporting its role in amplifying the inflammatory response." (PMID 40808852, 2025). "Contact with dental materials can, in fact, cause an inflammatory response with over-production of inflammatory markers such as IL6, IL-8, IL1β, IL-18, all of which play major roles gingivitis and periodontal destruction." (PMID 33211211, 2021). "Finally, gingivitis produced changes in saliva, with salivary levels of GM-CSF, IL-6, IL-7, IL-15, IP-10, KC-like, IL-10, IL-18, MCP1, TNFα being statistically significantly higher in the saliva of CG2 dogs compared to CG1." (PMID 38521919, 2024). "However, the IL-18 concentrations were significantly higher in the periodontally healthy subgroups than in gingivitis subgroups." (PMID 36769794, 2023). "However, there are also studies indicating decreased levels of IL-18 in gingival crevicular fluid in patients with gingivitis." (PMID 36289627, 2022). "GCF IL-18 levels were found higher in children with T1DM (n = 30) and gingivitis compared to healthy children with gingivitis (n = 13), while in a larger study GCF IL-18 levels were similar between diabetic (n = 44) and healthy children (n = 44) with gingivitis." (PMID 39000406, 2024). "There is, therefore, no clear consensus on the usefulness of IL-18 as an inflammation marker in gingivitis." (PMID 24790719, 2014).
hyperferritinemia (12 papers, 2012 to 2025). "Accordingly, IL-18/CXCL9 ratios were significantly higher in rheumatologic-associated hyperferritinemia compared to the other two subgroups." (PMID 39264477, 2024). "From a pathophysiologic standpoint, our patient’s striking hyperferritinemia and systemic inflammation reflect the central role of cytokine dysregulation, particularly IL-1β, IL-6, and IL-18, which drive the clinical phenotype and systemic inflammation." (PMID 41384165, 2025). "Hyperferritinemia in inflammatory and infective disorders is believed to be cytokine-mediated that implicate interleukin (IL) 1β, IL-6, IL-18, interferon (IFN)-γ, tumor necrosis factor-α (TNF-α) and macrophage-colony stimulating factor." (PMID 36844235, 2023). "Serum IL-18 levels were higher in patients with pleuritis, pneumonitis, abnormal liver function test, and hyperferritinemia (p < 0.05)." (PMID 33652679, 2021). "The development of MAS can be triggered by infectious diseases of viral or bacterial etiology and has been associated with exceptionally high serum levels of free IL-18 with concomitant hyperferritinemia, reflecting an IL-18/IL-18BP imbalance." (PMID 27977798, 2016). "IL-18 release induces ferritin, explaining the hyperferritinemia." (PMID 36250102, 2022). "The pathogenesis of hyperferritinemia is thought to be cytokine-mediated, with interleukin (IL)1a, IL1b, IL6, IL18, tumor necrosis factor-a, c-interferon, and macrophage-colony stimulating factor all implicated." (PMID 36425471, 2022). "The expression level of IL-37 was related to leukocytosis while IL-18 was related to pleuritis, pneumonitis, abnormal LFT, and hyperferritinemia." (PMID 33652679, 2021). "Regulation by proinflammatory cytokines such as interleukin (IL)-1b, IL-6, IL-18, MCSF, and INF-α provides a link to the disease pathogenesis and may explain rapid resolution of hyperferritinemia after targeted treatment and inhibition of key cytokines." (PMID 22536541, 2012).
leukemia (12 papers, 2014 to 2025). A malignant (clonal) hematologic disorder, involving hematopoietic stem cells and characterized by the presence of primitive or atypical myeloid or lymphoid cells in the bone marrow and the blood. "The IL18 (607C > A) rs1946518 A allele—particularly in AC and AA genotypes—was more prevalent among cases, suggesting an increased susceptibility to leukemia." (PMID 41257666, 2025). "The data indicate that the IL18 (−137G >C) variation may contribute to an elevated risk of pediatric leukemia development." (PMID 41257666, 2025). "In contrast, IL18 (607C > A) rs1946518 and IL18 (-137G > C) rs187238 polymorphisms may affect susceptibility to pediatric leukemia, indicating that IL18 could be a possible biomarker for the early identification of ALL." (PMID 41257666, 2025). "The study’s results indicate significant disparities in the distribution of the IL18 (−137G >C) rs187238 genotypes between children with leukemia and the control group." (PMID 41257666, 2025). "This study highlights the potential genetic influence of IL18 and MDR1 polymorphisms on pediatric leukemia susceptibility." (PMID 41257666, 2025). "Our results showed that caspase-1 inhibitor Z-YVAD-FMK down-regulated IL-1β and IL-18 secretion, suppressed proliferation and enhanced apoptosis of primary leukemia cells." (PMID 34211462, 2021). "IL-18 secreted by BM stroma elicits the growth of leukemia blast cells and contributes to progression of T-cell acute leukemia." (PMID 34084749, 2021). "As expected, our results showed that Z-YVAD-FMK decreased the secretion of IL-1β and IL-18 into culture medium of leukemia cells." (PMID 34211462, 2021). "Here, we demonstrated that NF-κB inhibitor Bay11-7082 decreased the secretion of IL-1β and IL-18 from leukemia cells and down-regulated the protein expression of pNF-κB, pro-caspase-1, pro-IL-1β, active caspase-1 and IL-1β." (PMID 34211462, 2021). "This suggests a lack of association between IL18 and leukemia, possibly indicating that IL18 demonstrates a more pronounced genetic influence in females than males." (PMID 41257666, 2025). "In a leukemia model, CD56dim NK cells activated by inflammatory cytokines IL-12, IL-15, and IL-18 will produce elevated levels of IFN-γ as part of a memory-like response when subsequently exposed to cancer cells, suggesting a possible anticancer role for this population." (PMID 36358824, 2022). "Moreover, ELISA results showed that Bay11-7082 inhibited the secretion of IL-1β and IL-18 from AML primary leukemia cells." (PMID 34211462, 2021). "Furthermore, human recombinant IL-1β and/or IL-18 were added into the culture medium of primary AML leukemia cells." (PMID 34211462, 2021). "We next investigated whether interfering with the IL-18 pathway affects leukaemia development in vivo." (PMID 24778454, 2014). "Although still preliminary, comparison of disease-free survival in T-ALL patients stratified according to the European Group of Immunological Classification of Leukaemia (EGIL) relative to their high/low IL-18 plasmatic level suggests that IL-18 levels may be of prognosis value in T-ALL." (PMID 24778454, 2014). "The cut-off values of serum IL-18 levels for the differentiation of s-JIA from KD, FMF, TRAPS, other subtypes of JIA, SLE, JDM, and leukemia were 4560, 4800, 1685, 1728, 2400, 2125, and 2240 pg/mL, respectively." (PMID 36211331, 2022). "We compared serum IL-18 levels in s-JIA and other inflammatory diseases and found they were significantly elevated in patients with s-JIA compared with Kawasaki disease (KD), TRAPS, other subtypes of JIA, SLE, Juvenile dermatomyositis (JDM), and leukemia." (PMID 36211331, 2022). "CCK8 results showed that IL-1β or IL-1β+IL-18 significantly stimulated the proliferation and inhibited the apoptosis of leukemia cells, but IL-18 alone had no obvious effects." (PMID 34211462, 2021).
leukemia (continued). "Our results showed that the culture medium of NLRP3-activated THP-1 cells inhibited primary leukemia cells apoptosis, and the inhibitory effect had partially reversed after neutralization with anti-IL-1β, while anti-IL-18 had no this effect." (PMID 34211462, 2021).
lymphopenia (12 papers, 2017 to 2024). Reduction in the number of lymphocytes. "Hyperinflammation may cause lymphopenia by inducing apoptosis, pyroptosis (both due to prolonged secretion of TNF-α, IL-6 or IL-18), or PANoptosis (due to the synergistic effect of IFNγ and TNF-α)." (PMID 39896810, 2024). "In addition, anti-IL-18, Il18r1 KO, Foxp3DTR, and Rag1 KO mice were also analyzed to investigate the effect of IL-18 signaling, regulatory T-cell (Treg) depletion, and permanent lymphopenia." (PMID 34493727, 2021). "Significant among them are neutrophilia, neutrophil-to-lymphocyte ratio (NLR), lymphopenia, inflammatory markers like C-reactive protein (CRP), and cytokines including interleukin-6 (IL-6), interleukin-8 (IL-8), interleukin-18 (IL-18), interferon-α (IFN-α), and tumor necrosis factor (TNF)." (PMID 35464560, 2022). "These include: lymphopenia; neutrophilia; neutrophil activation; increased intermediate and non-classical monocytes; high CD64 expression on monocytes and neutrophils; and raised levels of IL-6, IL-18, PAI-1, sCD25, sTNF-R, IP-10, MPO, and PTX3." (PMID 34632327, 2021). "Interestingly, the elevated IL-10 in the serum was correlated with the appearance of lymphopenia during FMDV infection but not IL-6, IL-2, IL-17, IL-18, IL-1β, TNF-α, IFN-α/β, TGF-β, and CXCL1." (PMID 34960627, 2021).
nasopharyngeal carcinoma (12 papers, 2011 to 2025). A carcinoma arising from the nasopharyngeal epithelium. "IL-18 polymorphisms at the promoter region have also been associated with variable risk of nasopharyngeal carcinoma." (PMID 34956172, 2021). "Accumulating evidence indicated that the IL-18 promoter genotype was correlated with the risk of PC, nasopharyngeal carcinoma (NPC), HCC and NSCLC." (PMID 31492049, 2019). "In conclusion, the present meta-analysis suggests that the -607C/A polymorphisms in IL-18 gene promoter is associated with a significantly increased risk of cancer, especially for nasopharyngeal carcinoma and esophageal cancer and in Asian population." (PMID 24130810, 2013). "For example, some studies found that -607 C/A polymorphism of IL-18 gene promoter was associated with increased risk of nasopharyngeal carcinoma and lung cancer." (PMID 24130810, 2013). "The present meta-analysis suggests that the -607C/A polymorphisms in IL-18 gene promoter is associated with a significantly increased risk of cancer, especially for nasopharyngeal carcinoma and esophageal cancer and in Asian population." (PMID 24130810, 2013). "In stratified analysis by cancer site, we found that -607C/A polymorphisms in IL-18 gene promoter was statistically related with an increased risk of esophageal cancer and nasopharyngeal carcinoma." (PMID 24130810, 2013). "Increased IL18 expression levels in nasopharyngeal carcinoma lead to poor prognosis." (PMID 38438469, 2024). "Studies have revealed that IL-1β/IL-18 can induce T and NK cell activation and killing and that IL-1β recruits neutrophils to control tumor growth and prolong survival in EBV-induced nasopharyngeal carcinoma model animals." (PMID 40982560, 2025).
Parkinson disease (12 papers, 2010 to 2025). A progressive degenerative disorder of the central nervous system characterized by loss of dopamine producing neurons in the substantia nigra and the presence of Lewy bodies in the substantia nigra and locus coeruleus. "Owing to the dual effect of Parkinson’s disease and surgical trauma, Aβ accumulation can activate NLRP3 and upregulate the expression levels of IL-1β, IL-18, and Caspase-1 to cause inflammation." (PMID 37232753, 2023). "Many inflammatory mediators known to increase with aging (IL-1β, IL-18, sTNF-R1) are upregulated to an even greater extent in neurodegenerative conditions such as AD and Parkinson’s disease (PD)." (PMID 35838044, 2022). "Mendelian randomization suggests that altering the expression of the NLRP3-inflammasome, IL-1β or IL-18, does not affect Parkinson's disease risk or progression." (PMID 37886468, 2024). "It was indicated that melatonin could regulate proliferation, differentiation, and survival of NSC by the neuroimmune-endocrine axis and the inhibition of interleukin-18 in the neurogenesis process of many neurological disorders such as Parkinson, Alzheimer, and ischemic brain injury." (PMID 35194433, 2021). "Several studies observed that physical training downregulated the expression of some pro-inflammatory cytokines (IL-1β, IL-18, TNF-α) and improved cognitive performance in different models of Alzheimer’s and Parkinson’s diseases, as well as patients." (PMID 36361978, 2022). "In mouse models of Parkinson’s disease, the downregulation of miR-30e, miR-190, and miR-7 enables NLRP3 and ASC expression, the cleavage of caspase-1, the release of IL-1β and IL-18 cytokines, and the cell death by pyroptosis." (PMID 34829842, 2021). "Exogenous administration of several miRNAs (miR-30e, miR-190, miR-7) to Parkinson’s disease mice models inhibits NLRP3, ASC, and caspase-1 expression, impairing the release of IL-1β and IL-18, limiting pyroptosis and, consequently, neuroinflammation and neuronal damage." (PMID 34829842, 2021). "Furthermore, via the activation of inflammasomes, especially NLRP3, the secretion of pro-inflammatory cytokines, such as IL-18 and IL-1β, are stimulated by α-SYN aggregates, a fact that establishes a negative correlation with the development of Parkinson’s disease." (PMID 39861194, 2025).